DICER1 (dicer 1, ribonuclease III)
Diseases named in the same sentence as DICER1 in open-access papers (continued):
Sharing a sentence is not in itself a finding about the gene and the disease.
colitis (7 papers, 2013 to 2025). Inflammation of the colon. "Our results differed from the observation in mice with dextran sodium sulfate [DSS]-induced colitis, in which knockout of Dicer1 gene increased susceptibility to colitis." (PMID 40926280, 2025). "Because the expression levels of DICER were retained in tumors and its surrounding tissues even after induction of colitis-associated tumors, the effects of Dicer1 deletion were cell-autonomous." (PMID 24023722, 2013). "To clarify the role of Dicer, we examined mice with intestinal epithelial cell-specific Dicer1 ablation in colitis-associated tumorigenesis." (PMID 24023722, 2013). "In the AOM-DSS mouse model, Dicer1 mRNA level was downregulated in colitis tissue and CAC tissue compared with normal colon tissue; the observed decrease in Drosha mRNA level was not significant." (PMID 25742789, 2015). "Immunohistochemistry also revealed that Dicer1 was downregulated in colitis tissue and CAC tissue compared with normal tissue." (PMID 25742789, 2015). "For example, when intestinal epithelial cells lack the enzyme Dicer1, which is essential for miRNA processing, the expression level of miRNA in gut contents and feces will be reduced, resulting in gut microbiota imbalance and severe colitis." (PMID 34203243, 2021). "To verify whether dysregulation of Dicer1 and Drosha participate in downregulation of miRNAs during CAC progression, we assayed the expression levels of Dicer1 and Drosha in AOM/DSS-induced colitis and in CAC mice and found that Dicer1 level was decreased during CAC progression." (PMID 25742789, 2015).
melanoma (7 papers, 2011 to 2022). A malignant, usually aggressive tumor composed of atypical, neoplastic melanocytes. "From a set of primary melanoma cell lines, Dicer1 locus showed 19.6% gain and 8.7% loss of DNA copy number." (PMID 21698147, 2011). "For example, as detailed thereafter, DICER1 is currently considered as a pivotal actor in melanoma biology." (PMID 29963229, 2018). "There was, however, a history of familial melanoma in DICER1 variant carrier relatives of Case 1, and although not considered to be associated to the syndrome, somatic DICER1 defects have been described in melanoma cases." (PMID 32714280, 2020).
Ovarian Sertoli-Leydig Cell Tumor (7 papers, 2014 to 2025). A benign or malignant sex cord-stromal tumor arising from the ovary. "Ovarian Sertoli-Leydig cell tumors (SLCTs) with androgenic manifestations harbor DICER1 mutations in 30–60% of cases." (PMID 30935425, 2019). "Pituitary blastomas are linked to a germline and somatic variation in DICER1, a key gene in microRNA processing, and may thereby be associated with other DICER1-related tumors, namely, ovarian Sertoli-Leydig cell tumor, renal tumors, soft tissue sarcomas, and several thyroid proliferations." (PMID 37519792, 2023).
poorly differentiated thyroid carcinoma (7 papers, 2020 to 2025). "Although far less common, more aggressive tumors such as pediatric poorly differentiated thyroid carcinoma and thyroblastoma have been shown to also harbor DICER1 mutations." (PMID 38254836, 2024). "Exceptions are clinically aggressive DICER1-mutated anaplastic thyroid carcinoma and childhood- and adolescent-onset poorly differentiated thyroid cancer (PDTC), although these tumors are rare." (PMID 34170462, 2021). "Additionally, poorly differentiated thyroid carcinoma and thyroblastoma were identified as potential indicators of somatic DICER1 mutations." (PMID 38254836, 2024). "Furthermore, poorly differentiated thyroid carcinoma and thyroblastoma should raise the concern for somatic DICER1 mutations." (PMID 38254836, 2024). "Two other neoplastic processes, poorly differentiated thyroid carcinomas (PDTC) and thyroblastomas, are specific manifestations of somatic DICER1-related disease." (PMID 38254836, 2024).
renal sarcoma (7 papers, 2018 to 2026). "In fact, the cartilaginous elements of her bladder tumor led us to question whether it could instead represent a distant recurrence of her renal sarcoma, although its distinct DICER1 mutation proved its independence." (PMID 31893257, 2018). "Moreover, sarcomas of the kidney and central nervous system have been identified as rare DICER1-related entities, highlighting the importance of genetic screening and close surveillance in all individuals with known or suspected germline DICER1 mutation." (PMID 41104964, 2025). "Given the association of pCN and DICER1 carriers, and the rare progression to ASK-DICER1 renal sarcoma, an abdominal ultrasound is recommended during infancy at the time a chest CT is done for PPB surveillance and every 6 to 12 months until at least 8-years of age." (PMID 34599283, 2022).
retinoblastoma (7 papers, 2013 to 2024). A malignant tumor that originates in the nuclear layer of the retina. "In an in vivo study, inactivating Dicer1 in a mouse model showed that it functioned as a haploinsufficient tumor suppressor in retinoblastoma and promoted hepatocarcinogenesis." (PMID 30833603, 2019). "In contrast to human ocular biology, loss of Rb1 is not sufficient to generate retinoblastomas in mice, and thus, similar underlying genetic differences may explain why loss of Dicer1 functions have not yet been associated with IO-MEPL-like lesions in previous mouse studies." (PMID 34785636, 2021).
acute myeloid leukemia (6 papers, 2015 to 2023). Acute myeloid leukemia (AML) is a group of neoplasms arising from precursor cells committed to the myeloid cell-line differentiation. "The overexpression of DICER1 protein, an essential enzyme involved in the processing of miRNA, results in the progression of acute myeloid leukaemia (AML)." (PMID 37624037, 2023). "For example, deletion of Dicer1, the key factor of microRNA maturation in osteoprogenitors, but not in mature osteoblasts, led to disruption of hematopoietic integrity and resulted in myelodysplasia and emergence of acute myelogenous leukemia (AML) in mice." (PMID 32474572, 2020). "In particular, the deletion of DICER1, an RNase III endonuclease responsible for miRNA biogenesis, in mesenchymal osteoprogenitors causes a hematopoietic disorder that recapitulates the human myelodysplastic syndrome, including the development of acute myeloid leukemia (AML)." (PMID 33922612, 2021). "In one seminal study, Raaijmakers and colleagues demonstrated that altering gene expression by deletion of Dicer1 specifically in osteoprogenitor cells, but not in the bone marrow, led first to the development of myelodysplasia and, subsequently, to the emergence of acute myeloid leukemia." (PMID 26543325, 2015).
bladder cancer (6 papers, 2013 to 2024). "For example, miR-200a inhibited DICER1 expression, therefore attenuating miR-16 maturation, leading to bladder cancer invasion and metastasis." (PMID 37495108, 2023). "Unlike FAH and COL7A1, DICER1 has been directly investigated for its role in bladder cancer patients." (PMID 38580653, 2024).
brain tumors (6 papers, 2021 to 2025). "Understanding how DICER1 gene mutations are linked to rare childhood brain tumors is challenging, mainly because these mutations are uncommon." (PMID 40361440, 2025). "Some of the frequently mutated genes have been rarely reported in brain tumors according to the COSMIC database: EPH2B (67% vs 1.11%), DICER1 (67 vs 1.25%), KMT2B (67% vs 1.46%), ATRX (67% vs 13.95%) as well as several muscular genes (DMD, MYO10, MYO9B, MYH6) (P < .00001, Fischer exact test)." (PMID 39233831, 2024). "This leaflet also comprises rare DICER1-associated tumors, like nasal chondromesenchymal hamartoma (NCMH) and primary brain tumors, for which we do not recommend standardized surveillance." (PMID 34170462, 2021).
chronic lymphocytic leukemia (6 papers, 2014 to 2020). "miR-130a also targets ATG2B and DICER1 to inhibit autophagy and trigger killing of chronic lymphocytic leukemia cells." (PMID 25544755, 2015). "Similarly, targeting of ATG2B and DICER1 by miR-130A inhibited autophagy in chronic lymphocytic leukemia cells, and knockdown of DICER1 alone was sufficient to block autophagy in this context." (PMID 28459042, 2017). "Additionally, miR-130a targets ATG2B and Dicer1 to inhibit autophagy and trigger the killing of chronic lymphocytic leukemia cells." (PMID 26375442, 2015). "For instance, silencing of Dicer1 in MEC-1 and primary chronic lymphocytic leukemia (CLL) cells leads to reduced autophagic flux by which several cancer cells exploit to overcome stress like starvation and hypoxia." (PMID 32774363, 2020).
goiter (6 papers, 2012 to 2025). Enlargement of the thyroid gland usually caused by lack of iodine in the diet, hyperthyroidism, or thyroid nodules. "While the common assumption is that pediatric goiters are associated with DICER1 gene mutations, individuals with these mutations can be diagnosed with goiters in their forties or later, particularly if they have not suffered from any other DICER1-related disorders." (PMID 39857323, 2025). "DICER1 variants are highly penetrant for goiter/thyroid follicular nodular disease (FND), especially in women: Three out of four women and one out of six men with germline DICER1 pathogenic variants will develop FND or undergo thyroidectomy before the age of 40." (PMID 40448797, 2025). "We conclude that germline DICER1 variants can be found in 11% of large goiters but no second-hit somatic mutation was found." (PMID 38330293, 2024).
male infertility (6 papers, 2011 to 2023). The inability of the male to effect fertilization of an ovum after a specified period of unprotected intercourse. "The results indicate that germ cell-specific deletion of Dicer1 or Dgcr8 resulted in reduced testis size and sperm count, and male infertility." (PMID 25244517, 2014). "Furthermore, elongated spermatids exhibit abnormal morphology and motility, and consequently, male infertility occurs in Dicer1-knockout mice, indicating that both Dicer1 and miRNAs play crucial roles in proper differentiation during spermatogenesis." (PMID 36531465, 2022). "Here, we investigated the deletion of Dicer1 in mouse postnatal male germ cells to determine how disruptions in miRNA processing may contribute to male infertility." (PMID 23056286, 2012). "In addition, male reproductive and sperm motility dysfunctions display an important redundancy among pathways modified in the cauda epididymidis (not shown), which is in accordance with the reduced sperm motility and male infertility phenotypes observed in the Dicer1 cKO mouse model." (PMID 27695046, 2016).
COVID-19 (5 papers, 2021 to 2023). A disease caused by infection with severe acute respiratory syndrome coronavirus 2. "On the other hand, the relative expression of hsa-miR-17-3p was up-regulated and its mRNA target (DICER1) was down-regulated with the increase of COVID-19 grade." (PMID 34256840, 2021). "In this study, six co-upregulated genes, RPS7, IGF1R, DICER1, ERH, MCTS1, and TNPO1, and two co-downregulated genes, FLNA and PXN, were identified from COVID-19 and thrombosis datasets." (PMID 35692833, 2022). "Based on bioinformatics analysis and previous studies, this study identified hub genes (RPS7, IGF1R, DICER1, ERH, MCTS1, TNPO1, FLNA, and PXN) that may contribute to the evaluation and treatment of COVID-19 and thrombosis." (PMID 35692833, 2022). "Conversely, in COVID-19 patients who respond to treatment (f), the relative expression of ZMYM5, COL5A3, and CAMSAP1 was significantly decreased and the relative expression of DICER1 was significantly increased during hospitalization." (PMID 34256840, 2021). "mRNA levels of AGO2, DICER1, DGCR8, DROSHA, and Exportin-5 (XPO5) were measured by quantitative reverse-transcription polymerase chain reaction (RT-qPCR) in nasopharyngeal swab specimens from patients with COVID-19 and controls, as well as in cells infected with SARS-CoV-2 in vitro." (PMID 37243263, 2023). "Our data showed that the mRNA expression levels of AGO2, DICER1, DGCR8, DROSHA, and XPO5 were not significantly different in patients with severe COVID-19 when compared to patients with non-severe COVID-19 and controls." (PMID 37243263, 2023). "Measured mRNA levels of AGO2, DICER1, DGCR8, DROSHA, and XPO5 were not significantly different in nasopharyngeal swab specimens of severe COVID-19 patients compared to non-severe COVID-19 patients or controls." (PMID 37243263, 2023). "In COVID-19 patients who did not respond to treatment (e), the relative expression of ZMYM5, COL5A3, and CAMSAP1 was significantly increased and the relative expression of DICER1 was significantly decreased during hospitalization." (PMID 34256840, 2021).
developmental delay (5 papers, 2022 to 2025). "Developmental delay is also a feature of GLOW syndrome (mosaic DICER1 variant in the RNase IIIb domain)." (PMID 34331184, 2023). "Some patients with DICER1 mutations have additional phenotypes, such as global developmental delay, macrocephaly, ASD, and other physical abnormalities." (PMID 35743796, 2022). "Mosaic somatic missense DICER1 variants in the RNase IIIb domain are linked to GLOW syndrome, an acronym from the reported core features of global developmental delay, lung cysts, overgrowth, and Wilms’ tumour (OMIM 618272)." (PMID 34331184, 2023). "In summary, germline pathogenic DICER1 variants may not only be associated with the occurrence of certain tumour types, but might also rarely include developmental features, like Pierre-Robin sequence, developmental delay, facial dysmorphisms, and ocular abnormalities." (PMID 34331184, 2023).
geographic atrophy (5 papers, 2013 to 2024). "Moreover, DICER1 deficiency in the retinal pigment epithelium has been associated with oxidative stress and geographic atrophy, and DICER1 knock-out mice develop prostate atrophy." (PMID 38637342, 2024).
granulosa cell tumor (5 papers, 2020 to 2025). A slow-growing, malignant tumor, characterize by the presence of granulosa-like cells and Call-Exner bodies, that is almost always found in the ovary. "Other alterations are fairly specific to subtypes of non-epithelial ovarian tumors, including the recurrent FOXL2 and common DICER1 mutations in adult granulosa cell tumors and Sertoli–Leydig cell tumors, respectively." (PMID 32485873, 2020). "In addition, DICER1 variant testing should be used to differentiate SLCTs and adult granulosa cell tumors with luteinized features: the presence of a DICER1 variant would favor the diagnosis of SLCT." (PMID 38136408, 2023). "In practice, in the case of an unusual morphology such as luteinized cells, the molecular pathology may help to rule out differential diagnoses: FOXL2 variant would favor a luteinized adult granulosa cell tumor while DICER1 variants could be seen in juvenile granulosa cell tumors." (PMID 38136408, 2023). "Concerning molecular pathology, DICER1 somatic variants have been identified in 19–40% of gynandroblastomas, especially in those with SLCT and juvenile granulosa cell tumor components (in both components); this somatic variant is sometimes associated with a germline variant." (PMID 38136408, 2023). "By definition, sex cord–stromal tumors NOS usually display no DICER1 nor FOXL2 variant since they may represent a distinct entity rather than a subgroup of adult granulosa cell tumors or SLCTS, although one case with DICER1 variant and few cases with FOXL2 variants have been reported." (PMID 38136408, 2023). "For pathologists, the main purpose of molecular biology in this case would be to rule out sex cord tumors, particularly adult granulosa cell tumors and SLCTS, by searching for FOXL2 and DICER1 variants in the case of fibroma with minor sex cord elements and/or ambiguous reticulin stain." (PMID 38136408, 2023). "As a result, the use of DICER1 gene testing to differentiate SLCTS and juvenile granulosa cell tumors or gynandroblastoma is not recommended." (PMID 38136408, 2023).
Myelodysplasia (5 papers, 2018 to 2025). Clonal hematopoietic stem cell disorders characterized by dysplasia (ineffective production) in one or more hematopoietic cell lineages, leading to anemia and cytopenia. "The strong diagnostic performance of DGCR8 and DICER1 supports their potential as early molecular indicators of disturbed miRNA biogenesis in myelodysplasia." (PMID 41463093, 2025). "Dicer1 was not disrupted in the leukemic cells, which instead displayed other genetic abnormalities, providing evidence that Dicer1 depletion from osteo-lineage cells caused myelodysplasia and AML in mice." (PMID 34746416, 2021). "Sbds deletion in murine osteoprogenitors resulted in leukopenia, lymphopenia, and myelodysplasia, thus recapitulating the phenotype of mice harboring Dicer1 deletion within the same cells." (PMID 36761941, 2023).
neurofibromatosis type 1 (5 papers, 2020 to 2025). A clinically heterogeneous, neurocutaneous genetic disorder characterized by cafe-au-lait spots, iris Lisch nodules, axillary and inguinal freckling, and multiple neurofibromas. "PAs have also been described in association with succinate dehydrogenase-related familial PA, neurofibromatosis type 1, and von Hippel–Lindau, DICER1, and Lynch syndromes." (PMID 33574795, 2020).
retinal degeneration (5 papers, 2020 to 2023). Degeneration of the retina. "In the case of the retina, Dicer1 KO in mouse RPC (thanks to the use of a Cre recombinase targeted by Vsx2/Chx10 regulatory sequences) has no obvious phenotype caused by developmental impairments but is characterized for a retinal degeneration at the second postnatal week." (PMID 36769311, 2023). "Concerning DP, MBD2 was involved in the formation of the eye, interacting both with HK2 and HIF1A, while PIWIL4 displayed an interaction with DICER1, which was involved in retinal degeneration." (PMID 37359372, 2023). "Remarkably, CFAP20 interacts with disease-causing proteins including: (i) ARL2BP, associated with RP, (ii) TBC1D32 and FOXJ1, related with ciliopathies, and (iii) LRRK2 and DICER1, involved in retinal degeneration in animal models." (PMID 35246562, 2022).
testicular germ cell tumor (5 papers, 2013 to 2023). A germ cell tumor arising from the testis. "As part of a recent study of DICER1 RNase III domains in 96 testicular germ cell tumors, a single RNase IIIb domain mutation was identified in a seminoma." (PMID 23547758, 2013). "To further explore the importance of DICER1 mutations in the etiology of testicular germ cell tumors (TGCT), we studied germ-line DNA samples from 43 probands diagnosed with familial TGCT." (PMID 23547758, 2013). "Indeed, the presence of cartilage in these DICER1-related teratoid thyroid neoplasms might have enhanced misinterpretation of malignant thyroid teratoma as being related to genuine germ cell tumors." (PMID 32507920, 2020).
tumor syndrome (5 papers, 2021 to 2025). "In patients with DICER1 and other gene mutations, the possibility of a tumor syndrome should be considered and genetic counseling should be done." (PMID 40161378, 2025). "Germline DICER1 mutations cause a defect of this physiologic gene silencing process, resulting in an extremely rare pediatric tumor syndrome." (PMID 35743266, 2022). "Despite DICER1 being classically associated with PPB, the expansion of our knowledge about the predisposition tumor syndrome and its associated tumors has shown that TFND is the syndrome’s most penetrant presentation, especially in females, with a calculated 10–20% penetrance in DICER1 carriers." (PMID 38254836, 2024).